PLK2 (polo like kinase 2)
Diseases named in the same sentence as PLK2 in open-access papers (continued):
Sharing a sentence is not in itself a finding about the gene and the disease.
tumor (71 papers, 2011 to 2026). "Examples include MANF, DCBLD2, and PLK2, which have been linked to tumor-suppressive functions in various cancers." (PMID 41154614, 2025). "VEGAF and PLK2 are representative markers associated with ITM in the primary tumours of patients with type III–IV recurrence." (PMID 39865865, 2025). "Plk2 deficient tumors grew much larger than control tumors suggesting a tumor suppressor function for Plk2." (PMID 22870256, 2012). "Notably, tumor-associated genes such as PLK2 and PIGN were among the DEGs activated specifically in cells producing the uS10 mutants." (PMID 35682850, 2022). "DNA damage and S-phase checkpoint defects in PLK2-deficient human tumor cells caused by replication stress eventually leads to increased cell death, suggesting that PLK2 plays an important role in maintaining stable replication and cell survival of human tumor cells." (PMID 35898867, 2022). "Besides tumor-associated roles, PLK2 is critically involved in the pathogenesis of Alzheimer’s disease as elevated levels promote production of amyloid beta plaques in a mouse model and also in synaptic plasticity." (PMID 34065956, 2021). "Collectively, these results underscore the critical role of the KDM5B/PLK2 axis in EBV-driven tumor progression and highlight its potential as therapeutic target in EBV-associated epithelial tumors." (PMID 40059116, 2025). "Our study further delineates a functional link where KDM5B downregulates PLK2 expression by reducing the H3K4me3 levels at the promoter, thereby activating the PI3K/AKT/mTOR pathway to promote tumor progression in EBV-associated epithelial tumors." (PMID 40059116, 2025). "This EBV-driven upregulation of KDM5B promotes tumor progression by repressing the tumor suppressor PLK2 through H3K4me3 demethylation, thereby activating the PI3K/AKT/mTOR pathway." (PMID 40059116, 2025). "This suggests a tumor-suppressive role for PLK2, found to be mediated by a direct interaction of PLK2 with PLK1, whose overexpression is involved in TNBC growth." (PMID 38473804, 2024). "In RP-7 treated cells, an enrichment of tumor suppressor genes namely, PLK2, and a decrease in prognostic markers like epidermal growth factor-like protein 8 were observed." (PMID 38272230, 2024). "A study has shown that PLK2’s significance in cancer is somewhat debatable; evidence points to both an oncogenic and a tumour suppressor role in a variety of malignancies." (PMID 36982508, 2023). "Given that the two closely related polo-like kinases, Plk2 and Plk3, are proposed to play tumor suppressor roles, the Plk1-specific inhibitory activity is an important property of Allopole-A." (PMID 37603740, 2023). "Promoter methylation induced by hypoxia and tumor downregulates the PLK2 expression, involved in development and progression of diseases." (PMID 35898867, 2022). "Among the DEGs that fell into this group, there were tumor-associated genes such as GADD45A, PPM1D, PLK2 and CREBRF." (PMID 35682850, 2022). "Contrariwise, other research found that PLK2 activity promotes tumor growth and inhibits apoptosis of colorectal cancer cells in vitro and in vivo." (PMID 35053604, 2022). "Some of cell cycle pathways were also associated with a downregulation of polo-like kinases PLK1 and PLK2; the roles of these in cancer is quite controversial where findings suggest both oncogenic and tumor suppressor roles in various cancers." (PMID 35600164, 2022).
tumor (continued). "In both complete carboplatin responders and partial responders, PDX models with lower PLK2 expression had a better response to volasertib, which induced tumor cytostasis (BCM-0002 vs. BCM-7482, BCM-2665 vs. BCM-15003)." (PMID 35156101, 2021). "In contrast, tumor models with higher PLK2 expression continued to grow under volasertib administration, although at a slower rate compared with their controls." (PMID 35156101, 2021). "Comparison of PLK2-low PDX lines to PLK2-high PDX lines when log2 fold change of control groups reached 2.5 suggested that volasertib has a better tumor growth–inhibitory effect in PLK2-low PDX lines." (PMID 35156101, 2021). "Downregulation of PLK2 promotes tumor aggressiveness and chemo resistance via activation of notch axis and PLK2 overexpression reduces malignant behavior both in vitro and in vivo." (PMID 34065956, 2021). "The tumor-suppressive role of PLK2, and its relationship with oncogene PLK1, provide a mechanistic rationalization to use PLK1 inhibitors in combination with chemotherapy to treat PLK2-low/deleted tumors." (PMID 35156101, 2021). "Notwithstanding the delayed growth kinetics, together with the doxycycline-inducible PLK2 mouse tumor model, we demonstrated that a higher level of PLK2 expression was able to impair the therapeutic effect of volasertib at the experimental endpoint." (PMID 35156101, 2021). "Statistical analysis comparing the log2 fold change in different tumor types when the control treatment group reached approximately 1,500 mm3 confirmed the significant differences among these models as a function of Plk2 expression." (PMID 35156101, 2021). "Strikingly, doxycycline induction of PLK2 expression resulted in decreased volasertib inhibition of tumor growth at the experimental endpoints in both models." (PMID 35156101, 2021). "Subsequently, we performed a colony transformation assay and found that knockdown of PLK2 in TLM-HMECs using two different shRNAs, both increased the number of colonies as compared with controls, consistent with the tumor-suppressive role of PLK2." (PMID 35156101, 2021). "PLK2 is a cell‐cycle regulatory gene that affects tumor cell‐cycle progression, cell proliferation, and individual bone development." (PMID 32349184, 2020). "In an established PDX animal model with abundant TAp73 levels, PLK2 inhibition or CDDP treatment prevented tumor growth and prolonged median survival." (PMID 32349184, 2020). "As we previously demonstrated that PLK2 functions as a tumor-suppressor gene and attenuated chemoresistance in GBM, it is essential to deeply investigate the underlying signaling pathways regulated by PLK2." (PMID 33176854, 2020). "Consistent with the findings of previous studies, the results of this work showed that PLK2 promoted clone formation in PDX‐OS cells, indicating that PLK2 has a protective effect on tumor cells." (PMID 32349184, 2020). "Kaplan-Meier analysis showed elevated PLK2 suppressed the in vivo tumor growth thus prolonged the survival of xenograft mice." (PMID 33176854, 2020). "Summarized, whereas PLK2 and PLK3 are considered to be tumor suppressors, PLK1 and PLK4 are associated with carcinogenesis and are often overexpressed in tumor cells." (PMID 33053667, 2020). "PLK2 has been reported to act as a tumor suppressor gene but sometimes plays an oncogenic role in tumors." (PMID 32231136, 2020). "This study also revealed a two-faced nature of PLK2: In a healthy cell, it plays a role of a tumor suppressor—by its involvement in the spindle checkpoint it ensures a genetic stability and inhibits neoplastic transformation." (PMID 33287223, 2020).
tumor (continued). "High expression of PLK2 in tumor cells can promote tumor progression and drug resistance and affect the prognosis of patients." (PMID 32349184, 2020). "In our study, we found that PLK2 was significantly down-regulated in 529 GBM tissues compared to 10 normal non-tumor tissues (log2FC = −1.479; P-value < 0.0001) on AffyU133a platform." (PMID 31763067, 2019). "Polo-like kinase 2 (Plk2) was found to instigate tumor growth and evade apoptosis in CRC cells in vitro and in vivo by degrading FBXW7 which rendered subsequent stabilization of cyclin E." (PMID 30791487, 2019). "The tumor suppressor PLK2 inhibited SiHa cell proliferation, reduced cell viability, and promoted paclitaxel/cisplatin -induced apoptosis." (PMID 26910911, 2016). "Since both Plk2 and Plk3 are required for promoting cell survival and they exhibit properties similar to tumor suppressors, specific inhibition of Plk1, but not Plk2 or Plk3, would be important for selectively killing cancer cells, but not normal cells." (PMID 26500787, 2015). "Other TAZ downstream target genes including IRS-1, MYLK/MLCK, and PLK2 are also important for tumor development and metastasis." (PMID 25940705, 2015). "According to the expression level of mir-27a in LSCC, we have selected a presumable tumor suppressor gene PLK2 as a potential target of miR-27a among the predicted genes." (PMID 25239093, 2014). "Further, we were able to show in the same series that for patients for whom methylated PLK2 was detected in either or both tumour tissue and matched serum there was reduced survival, shown by Kaplan-Meier analysis." (PMID 22289679, 2012). "Complete resistance to camptothecin was shown which pointed to an interplay between Plk2 and tumour micro-environment, whereas in the same experiments normoxia was associated with increased drug sensitivity." (PMID 22289679, 2012). "PLK2 plays a critical role in cellular stress response,redox regulation,and tumor progression." (PMID 41405409, 2026). "Moreover, in vivo xenograft models clearly showed that PLK2 overexpression significantly curtailed the tumor growth boosted in CNE2-EBV and AGS-EBV cells due to KDM5B overexpression." (PMID 40059116, 2025). "First, given that KDM5B is a master histone modifier, additional downstream factors, beyond PLK2, may contribute to KDM5B-induced tumor progression in EBV-associated epithelial malignancies." (PMID 40059116, 2025). "Plk2 is recognized as a tumor suppressor in several cancers." (PMID 35842499, 2023). "Since the NLRP3 inflammasome can be formed and activated by DAMPs, PLK2-induced DAMPs release could also be important for GSDMD pathway activation in USP18 depleted tumor environment in vivo." (PMID 36646704, 2023). "Plk2 has also been recognized as a tumor suppressor in several cancers." (PMID 35842499, 2023). "The overexpression of PLK2 can promote the growth of many tumor types and inhibit their apoptosis." (PMID 36684674, 2023). "It was reported that PLK2 promotes tumor growth by targeting the FBXW7/ Cyclin E pathway." (PMID 35840978, 2022). "The measured tumor diameter of human PLK2 deficient NSCLC cell xenograft is larger in mice; Interestingly, in vitro cell culture suggests that anti-tumor effect of PLK2 might result from a response to hypoxic tumor microenvironment (TME)." (PMID 35898867, 2022). "Like its compatriots, the role of PLK2 in tumor has attracted considerable attention." (PMID 35898867, 2022).
tumor (continued). "Previously, we have found that Plk2 had a high expression in tumour tissues and might be an independent prognostic marker for CRC patients." (PMID 35579380, 2022). "PLK2 is reported to be a tumor suppressor in solid organ tumor as well." (PMID 35898867, 2022). "In our study, higher PLK2 expression indicated a stronger anti-tumor effect." (PMID 36558006, 2022). "In addition, in hematological neoplasma, most of the current studies believe that PLK2 acts as a tumor suppressor, and the kinase activity of PLK2 is also involved in the pathological mechanism of neurodegenerative diseases such as PD." (PMID 35898867, 2022). "For all this, the role of PLK2 in solid organ tumor is still elusive and more reports indicate PLK2 could exacerbate tumor progression." (PMID 35898867, 2022). "The tumor-inhibiting effect of PLK2 might also be related to the mammalian target of rapamycin (mTOR) signaling pathway." (PMID 35898867, 2022). "Knockdown of PLK1 alone did not significantly change the number of colonies formed, but instead it mitigated the increased colony formation observed following PLK2 knockdown, thus suggesting that the tumor suppressive function of PLK2 is specifically related to PLK1 activity." (PMID 35156101, 2021). "Therefore drugs targeting this pocket address also other kinase domains affecting, among others, the tumor suppressor functions of PLK2 and in particular of PLK3 leading to adverse side effects." (PMID 34065956, 2021). "PLK2 is downregulated in several cancers and therefore has been considered as a tumor suppressor." (PMID 34065956, 2021). "Moreover, the xenograft mouse model illustrated that PLK2-OE prolonged the overall survival of tumor-bearing mice and consistently increased the chemosensitivity to TMZ." (PMID 33176854, 2020). "However, there was a high variability of Plk2 and Plk3 in both patient samples and cell lines and thus, more data on Plk2 and Plk3 expression in tumor cells relative to normal cells need to be gathered." (PMID 32060361, 2020). "However, other tumor studies have shown that the expression of PLK2, as a tumor promoter, has a controversial effect on the survival and prognosis of patients." (PMID 32349184, 2020). "Previous studies 46 verified that PLK2 could inhibit the functional activity of TAp73 against OS, reduce apoptosis in tumor cells, and maintain the proliferation of OS cells." (PMID 32349184, 2020). "In this study, we analyzed the immunohistochemistry data of the tumor suppressor gene TAp73 and the tumor‐promoting gene PLK2 in clinical specimens and found that there is heterogeneity in the expression of TAp73 and PLK2 in OOS and COS cells, which affects the prognosis of patients." (PMID 32349184, 2020). "In PDX‐OS1 cells with high basal expression of TAp73, PLK2 inhibition alone prevented late OS cell proliferation, and CDDP combined with inhibition of PLK2 by either siRNA or a PLK2 inhibitor significantly inhibited tumor cell proliferation in both OS cell lines." (PMID 32349184, 2020). "Similarly, PLK2 expression was significantly lower in 154 GBM tumor tissues than that in five corresponding non-tumor tissues on IlluminaHiSeq platform (P < 0.0052)." (PMID 31763067, 2019). "Based on its cell cycle regulator function PLK2 is known as a tumor suppressor." (PMID 29287594, 2017). "Both Plk2 and Plk3 are proposed to function as tumor suppressors." (PMID 26500787, 2015). "Whilst there is good experimental evidence that Plk1 may function as an oncogene and indeed is a leading target for developmental therapeutics in oncology, Plk2-Plk5 have properties more consistent with tumour suppressor genes [review 1]." (PMID 22289679, 2012). "Hence, PLK2 overexpression could potentially be leveraged as a therapeutic strategy to inhibit tumor progression and enhance apoptosis, providing new avenues for GBM treatment." (PMID 39927502, 2025).
tumor (continued). "Our findings suggest that PLK2 may potentially function as a tumor suppressor in GBM." (PMID 39927502, 2025). "This research found that binding of PLK2 to the tumor suppressor Fbxw7 resulted in increased degradation of Fbxw7 and stabilization of Cyclin E; this suggested that PLK2 may act as a tumor supportive factor, may serve as a prognostic and diagnostic target and furthermore as a therapeutic target." (PMID 35053604, 2022). "Therefore, the role of PLK2 appears to be tumor type- and/or stage-dependent." (PMID 35156101, 2021). "In addition, PLK2 inhibition could also slow tumor growth and prolong the median survival of the PDX host." (PMID 32349184, 2020). "In addition, PLK2 was proved to be a tumor suppressor in SiHa cells." (PMID 26910911, 2016). "RT-qPCR analyses in both EBV-negative and -positive epithelial tumor cells, as well as those cells with KDM5B knockdown or overexpression, pinpointed PLK2 as the primary target with the most significant alterations affected by KDM5B." (PMID 40059116, 2025). "The results indicated that CDC73, PSMC2, SOCS3, and ETV4 were substantially upregulated in tumor group than that in control group, whereas PLK2 and LMO7 were substantially downregulated in tumor group than that in control group." (PMID 41318472, 2025). "The data showed that in the control group, the tumor tissue grew rapidly, whereas in the CDDP treatment, PLK2 inhibitor treatment, and the combination treatment groups, tumor growth was significantly inhibited (P < .05)." (PMID 32349184, 2020). "In contrast, the RNA expression levels of the two most closely related PLK family members, PLK2 and PLK3, were both lower in the tumor specimens (0.66 and 0.48-fold, respectively)." (PMID 29228663, 2017). "Furthermore, KDM5B knockdown significantly inhibited NPC cell proliferation, while the suppressive effects were largely rescued by PLK2 knockdown, suggesting that PLK2 is a major downstream mediator of KDM5B-induced tumor progression." (PMID 40059116, 2025). "Among these genes was the atypical ISG polo like kinase 2 (PLK2), a gene that is downregulated in AML patients and thus may play a tumor suppressive role in cancer." (PMID 36646704, 2023). "In contrast with the control group, PLK2 inhibitor treatment remarkably restrained tumor growth and there were no remarkable toxic effects in the treatment group." (PMID 35256538, 2022). "Although it is reported that PLK2 is highly expressed in MM and facilitates tumor cell vitality by inhibiting KIRA8 induced CHOP mediated apoptosis, more studies have showed PLK2 acts as a tumor suppressor in hematological neoplasma." (PMID 35898867, 2022). "Moreover, our previous investigation suggested that PLK2 promoted tumor growth and restrained cells apoptosis, while PLK3 seemed to have tumor-suppressive feature in CRC." (PMID 31655629, 2019). "Unlike Plk1 that promotes cell cycle progression, Plk2 and Plk3 have been identified as tumor suppressors to prevent mitotic catastrophe and preserve genomic integrity." (PMID 27902479, 2017). "In the cases with miR-27a up-regulation, PLK2 protein expression level was significantly lower in cancer tissues than that in the adjacent non-tumor tissues, which showed a negative correlation with miR-27a expression level." (PMID 25239093, 2014).